ATM (ATM serine/threonine kinase)
Diseases named in the same sentence as ATM in open-access papers (continued):
Sharing a sentence is not in itself a finding about the gene and the disease.
cancer (continued). "Conversely, more normal alveolar structures and a significant drop of the number of cancer nests were found in ATM depletion condition." (PMID 27556690, 2016). "Our dimeric ATM/Tel1 structure provides an initial molecular blueprint for the development of potential radiosensitizers for cancer radiotherapy." (PMID 27229179, 2016). "A similar nuclear distribution was found for human phospho-Thr390 GSK3β in a human cancer cell line following treatment with doxorubicin, and this was prevented by inhibiting ATM." (PMID 26822034, 2016). "Inhibition of aberrantly active DDR signaling pathway has become an attractive therapeutic strategy in cancer therapy with highly selective small molecule inhibitors of ATM and ATR signaling in preclinical and clinical development, respectively." (PMID 27391441, 2016). "Our results also revealed that the ATM-KD protein physically blocks strand cleavage in a MRN-dependent manner, further suggesting the level of mutant ATM protein and MRN status can modify both the cancer risk and therapeutic responses." (PMID 27304073, 2016). "The results indicate that there is not a statistically significant relationship between the presence of ATM mutations and MAPK7 mRNA content in human cancer." (PMID 27793024, 2016). "In the presence of higher levels of miR-302b, reduced levels of E2F1 result in the partial abrogation of ATM activation, affecting cancer cell ability to repair DNA and proliferate." (PMID 26623722, 2016). "As ATM is commonly mutated in human cancers, the next steps that follow on from this research are to develop methods to test which cancers contain the inactive form of the ATM enzyme." (PMID 27304073, 2016). "The search for specific modulators of ATM is beneficial not only to for understanding the principle functions of this kinase but also for their potential clinical application to sensitize cancer cells to anticancer therapy." (PMID 26824362, 2016). "The study of ATM function in cancer is further complicated by its involvement in other processes, including metabolic homeostasis." (PMID 27922010, 2016). "The prompt activation of DDR by ATM following exposure to IR is crucial for cancer cells to engage in DNA repair and prevent the activation of programmed cell death." (PMID 26943034, 2016). "The proportion of NSE-containing RNAs was on average higher in leukemic cells than in normal cells, with some samples exhibiting very high levels, potentially contributing to reduced ATM expression in cancer cells." (PMID 26732650, 2016). "For example, whereas VP-16 provokes ATR activation, camptothecin activates either ATM or ATR in DNA damage events in different cancer cell lines." (PMID 26683224, 2016). "Four genes (AKAP9, ATM, CREBBP, and NF1) were mutated in only one subject but were reported on the Cancer Gene Census list, and the mutations were predicted to be detrimental by SIFT." (PMID 27689332, 2016). "Previous studies have shown a close relationship between ATM activity and activation of MAPKs in cell cycle arrest, senescence, migration and apoptosis in cancer cells." (PMID 26465009, 2015). "Here, we studied the contribution of the DDR kinase, ATM, in metastatic programs operating in cancer cells." (PMID 26030852, 2015). "Ataxia-telangiectasia mutated (ATM) protein kinase regulates the DNA damage response (DDR) and is associated with cancer suppression." (PMID 26030852, 2015).
cancer (continued). "While the in vitro data is convincing, an in vivo xenograph model would be more compelling evidence to suggest that combining BO-1055 and ATM/ATR inhibitors effectively decreases the survival of cancer cells." (PMID 26208482, 2015). "Meanwhile, the DNA damage sensor ATM is integrated into this process, and the depletion of ATM will assist cancer cells toward apoptotic destiny." (PMID 26649750, 2015). "ATM is frequently altered or deleted in several types of human cancers, in particular in haematological cancers." (PMID 26610585, 2015). "The combined 208 cases yielded no additional high-frequency mutated genes, however, multiple lower frequency (<2.5% recurrence) cancer-related genes were identified including ATM, ARID2, TGFBR2 and ACVR1B." (PMID 25855536, 2015). "Response of cancer cells to chemotherapy-induced DNA damage is regulated by the ATM-Chk2 and ATR-Chk1 pathways." (PMID 26544894, 2015). "Inhibition of cell cycle checkpoints mediated by CHK1 and CHK2 or proteins involved in BER, such as APE or POLQ, or in DSBs repair, like ATM or DNA-PK, have indeed been shown to sensitize cancer cells to radiotherapy." (PMID 25954303, 2015). "Ionizing radiation has been reported to induce ATM-Chk2-dependent checkpoint signaling followed by a G2/M cell cycle arrest, believed to drive sub-lethally damaged cancer cells toward apoptosis." (PMID 25460508, 2015). "IR induces Ataxia-telangiectasia mutated (ATM)- and Chk2-dependent checkpoint signaling, and this induces apoptosis in sublethally damaged cancer cells." (PMID 26320178, 2015). "ATM provides another close genetic link between neurodegeneration and cancer through genome integrity maintenance and cell cycle control." (PMID 26504519, 2015). "We observed several significant associations in specific cancer types: RAD51C in AML, ATM in PRAD and PALB2 in STAD." (PMID 26689913, 2015). "Oxidative stress—a build-up of harmful chemicals inside cells—is a signature feature of cancer cells and is known to be another signal that activates ATM." (PMID 26030852, 2015). "As ATM has been shown to directly phosphorylate Akt and promote cell survival, ATM inhibition is widely used as an anti-tumor strategy in several types of cancer." (PMID 26465009, 2015). "Our work provides a rationale for evaluating the clinical efficacy of IL-8 inhibition in the context of lung metastasis, including the use of ATM inhibitors beyond their ability to radio-sensitize cancer cells." (PMID 26030852, 2015). "By identifying IL-8 as a target of oxidative stress and ATM, we provide a link between activated ATM by oxidative stress and pro-metastatic pathways operating in cancer cells." (PMID 26030852, 2015). "ATM mRNA itself is also targeted by some miRNAs up-regulated in cancer, such as the N-myc-induced miR421, but also miR101 and miR100 whose overexpression enhances radiosensitivity by down-regulating ATM." (PMID 26617633, 2015). "On the one hand, ATM serves as a tumor suppressor to limit the proliferation or survival of cancer cells during primary tumor formation." (PMID 26030852, 2015). "Further, loss of DDR components ATM, ATR, or CHK1 lead to either embryonic lethality in mice and/or a predisposition for cancer." (PMID 25898113, 2015). "Understanding the crosstalk between the NF-κB and ATM signaling in complex pathologies including inflammation and cancer remains an area of active investigation." (PMID 26030852, 2015).
cancer (continued). "The experiments reveal that reducing the amount of ATM in cancer cells actually made them less able to migrate and less invasive." (PMID 26030852, 2015). "In our study, the only significant associations with ATM p.Asp1853Asn and ATP7B p.Arg952Lys variants indicated the importance of cell cycle and cellular copper metabolism control systems in the cancer-prone phenotype." (PMID 25591549, 2015). "Therefore, it is possible that the presence of triptolide may also increase the cisplatin-induced apoptosis of A549 and HTB182 lung tumor cells by inhibiting the NER activity, which increases DSBs for cisplatin-treated cancer cells and causes activation of the ATM pathway." (PMID 26161259, 2015). "One of the ATM mutations identified is R3008H, also found in our study, and included in the COSMIC database due to its known association with cancer." (PMID 26536348, 2015). "While high-ATM expression levels were detected in 44% (n=15/34) of low-grade carcinomas (WHO Grade I and II), this was the case in just 17% (n=4/23) of high-grade tumours (WHO Grade III and IV)." (PMID 26220524, 2015). "In a recent pre-clinical study, we have demonstrated that ATM, DNA-PKcs and ATR inhibitors are synthetically lethal in XRCC1 deficient cancer cells." (PMID 26674120, 2014). "Based on a recent study from our group demonstrating a functional interplay between ataxia-telangiectasia mutated (ATM) and ARF during carcinogenesis, we discuss the role of ARF at the crossroads of cancer and developmental processes." (PMID 25101116, 2014). "To date, the ATM protein kinase has been straightly considered to be a DNA damage sensor and one of therapeutic targets for cancer." (PMID 25541996, 2014). "Overall, these findings provide support, but at the same time raise some concerns about the pharmacological targeting of ATM in cancer therapy." (PMID 24681585, 2014). "BRCA1/2 somatic mutation or promoter methylation, ATM mutation, MRE11-dominant negative mutations in MMR-deficient cancers, FANCF promotor methylation and PTEN deficiency are all potential biomarkers of sensitivity to PARPi." (PMID 24616882, 2014). "A second hint comes from the observation that WIP1, a Ser/Thr phosphatase aberrantly upregulated in cancer that dephosphorylates and modulates, among other targets, also ATM activity, is involved in the modulation of the SHH signaling." (PMID 24681585, 2014). "Our results are in agreement with previous studies showing the mechanism underlying the anticancer effect of DAC treatment, and its involvement in activation of the ATM signaling pathways in cancer cell lines." (PMID 25077705, 2014). "Components of the FA pathway has been found to be lost or defective in a range of human cancers and are characterized by hypersensitivity to DNA crosslinking agents, chromosomal instability and reliance on DNA repair mediated by ATM." (PMID 24913641, 2014). "MDC1 majorly functions as a mediator in the DDR, which mediates the recruitment of other DDR proteins, such as ataxia telangiectasia-mutated (ATM), Breast Cancer 1, Early Onset (BRCA1), Mre11/Rad50/NBS1 (MRN) complex, to the site of damage." (PMID 25198518, 2014). "This review aims to give a complete overview on the work of several labs that links ATM to the control of the balance between cell survival, proliferation and death in cancer." (PMID 24681585, 2014).
cancer (continued). "Here we will review evidence for a role of ATM in these pathways and discuss their significance in cancer initiation and development." (PMID 24681585, 2014). "One major problem behind the idea of targeting ATM activity for cancer therapy comes from the observation that the output of the inhibition of ATM activity does not fully mimic the effect of ATM loss of expression." (PMID 24681585, 2014). "Although it has been reported that ionizing radiation can induce NKG2D ligands on cancer cells by activating the ATM-ATR pathway, the precise regulatory mechanism involved is unclear." (PMID 24512718, 2014). "We found recurrent mutations in 4 cancer genes and delineated that NRAS, KRAS and ATM mutations are distributed in a mutually exclusive fashion." (PMID 25115387, 2014). "We demonstrate for the first time that treatment of cancer cells with DhL, promotes the accumulation of DNA damage markers such as phosphorylation of ATM and focal organization of γH2AX and 53BP1." (PMID 23341930, 2013). "Inhibition of ATM using KU-55933 (KU) is shown to increase reactive oxygen species (ROS) in cancer cells." (PMID 24358288, 2013). "Ataxia telangiectasia (A-T) is a human disease caused by ATM deficiency and characterized by the failure of CCL checkpoints, predisposition to cancer, immunodeficiency and by neurologic abnormalities caused by significant loss of neurons." (PMID 23861893, 2013). "Other studies have shown selective killing by PARP inhibition of cells from diverse tumor types bearing mutations in ATM, MRE11A, BRCA2, or the EWS-FLI1 translocation, suggesting that PARP is a bona fide hub for genetic interactions with cancer genes." (PMID 23390603, 2013). "Genes involved in cancer progression were also readily identified (as outlined for ATM and MXI above), and these also included WRAP53 as AS." (PMID 23383294, 2013). "For example, VP-16 elicits primarily ATR activation, however, camptothecin activates either ATM or ATR in DNA damage events in different cancer cell lines, to some extent, was similar to RD in PCa cells." (PMID 24069304, 2013). "At least 76 large functions groups were significantly (p<0.01) affected after the depletion of ATM, with several cancer and tumor specific functions being highly affected." (PMID 23741392, 2013). "Amongst the top fourfunctional groups of genes, the Cell Cycle:G2/M DNA Damage Checkpoint Regulation and ATM Signalingpathways was directlylinked to cancer." (PMID 22892065, 2012). "Single amino acid substitutions in the ATM gene are the most common forms of genetic variations that account for various forms of cancer." (PMID 22529920, 2012). "In cancer cells exposed to hypoxia, ATM remains diffuse throughout the nucleus, as does phosphorylated ATM." (PMID 22768306, 2012).
cancer (continued). "Understanding the mechanism of serum starvation-induced ATM activation in cancer cells is beyond the scope of the present study and future work will address this issue." (PMID 23211021, 2012). "Recently, polymorphisms on 53BP1 and ATM genes were studied for their role on cancer development, and since oncogenic viruses might interact with these proteins there is a great need to evaluate the possible role of polymorphisms on these proteins in viral associated cancer development." (PMID 22200742, 2012). "Of note, our current findings demonstrate that low metformin concentrations cannot activate the ATM/AMPK tumor suppressive axis when cancer cells import thymidine and hypoxanthine from the extracellular milieu." (PMID 22837425, 2012). "It is widely used plant in complementary and alternative treatment method (CTM and ATM) as cancer, and so forth." (PMID 22593694, 2012). "Caffeine, an AMPK activator, has been shown to sensitize cancer cells to the growth inhibitory effects of the antifolate pemetrexed by potentiating pemetrexed's ability to induce ATM phosphorylation." (PMID 22837425, 2012). "The first network suggests significant involvement of p30-interacting proteins with DNA recombination, repair, cell cycle and cancer with pathways clustering around ATM, cyclin E, cyclin A and CDK2." (PMID 22876852, 2012). "Nevertheless, even after >20 passages, these ATM-depleted cells were only able to form dysplastic lesions and unable to form malignant tumors in immunodeficient mice, suggesting that an additional event must occur before adopting a malignant phenotype." (PMID 23251624, 2012). "The other possible reason is that ATM utilizes diversity mechanisms that regulate cell proliferation or apoptosis in different cancer cells." (PMID 22276117, 2012). "Perhaps the most significant contribution to understanding atm-1, and ATM in general, would be discovering novel therapeutic targets for ATM-driven cancers." (PMID 22350747, 2012). "To date, many molecular epidemiological studies have evaluated the role of ATM IVS 22–77 T>C in cancer development within populations of different ethnicities." (PMID 22276117, 2012). "In this respect, it is very relevant that reversible ATM inhibitors have recently been described and that transient ATM inhibition was shown to reach radiosensitising effects in cancer cells." (PMID 22323184, 2012). "Recent studies in cancer cells demonstrate alternate mechanisms for activating ATM under hypoxic conditions, including the increase of radical oxygen species, oxidative stress and DNA breaks." (PMID 22768306, 2012). "Recently, ATM inhibitors were demonstrated to enhance radiation sensitivity of cancer cells and suppression of the proliferation of tumor cells." (PMID 21935375, 2011). "Of 608 cancer-related genes, 32 including RON/MISTR1, ATM (ataxia teleangiectasis mutated) and FANCM (Fanconi anemia M protein) were affected by amiloride." (PMID 21694768, 2011). "Inhibitors of important molecules in double-strand breaks repair, such as ATM or DNA-dependent protein kinase (DNA-PK), have been shown to sensitize cancer cells and xenografted tumors to radiotherapy." (PMID 24213112, 2011). "Several studies support resveratrol inducing a sustained DNA damage response via BRCA1 and activation of the ATM/ATR-Chk1/2-Cdc25C pathway in cancer cells." (PMID 22247744, 2011).